APAF1 (apoptotic peptidase activating factor 1)
Diseases named in the same sentence as APAF1 in open-access papers (continued):
Sharing a sentence is not in itself a finding about the gene and the disease.
tumor (118 papers, 2002 to 2025). "The results showed that supernatant of M1-iBMDMs promoted the expression of apoptosis associated genes, including APAF1 and Caspase-9 in tumor cells, and decreased the level of protective molecule BCL2." (PMID 38650937, 2024). "The in vivo loss of APAF-1 expression is generally associated with tumor progression and its up-regulation is associated with the antitumor activity of taxane." (PMID 35736153, 2022). "Loss of pro-apoptotic protein Apaf-1 can aid tumor cells in evading programmed cell death or apoptosis." (PMID 28399853, 2017). "Loss of Apaf-1 expression can aid tumour cells in evading immune attack-induced death and/or Caspase-9 mediated apoptosis, resulting in metastasis." (PMID 28479926, 2017). "In conclusion, the present study is consistent with some observations in oncogenesis that have identified the loss of APAF1 as a substantial characteristic in development of tumor." (PMID 28875006, 2017). "In summary, the present study is consistent with some observations in oncogenesis that have identified the loss of APAF1 as a substantial characteristic in development of tumor." (PMID 28875006, 2017). "Expression of TNF-α and Apaf-1 was significantly associated with tumor thickness, and osteopontin expression correlated with increased tumor cell proliferation (Ki-67)." (PMID 19061491, 2008). "Apaf-1 expression was also associated with increased tumor thickness and strong staining of the pro-invasive αv-integrin." (PMID 19061491, 2008). "Additionally, low APAF1 expression was significantly associated with tumor malignancy and a higher rate of recurrence and metastasis." (PMID 39364485, 2024). "We postulate that TH causes the up-regulation of Apaf-1 and Caspase-9 expression and may activate the intrinsic apoptotic pathway to modulate tumor growth." (PMID 28399853, 2017). "The heightened sensitivity to apoptosome activation in these tumours may be caused by overexpression of both Apaf-1 and PC-3 proteins." (PMID 24626292, 2014). "TGF-β1, a critical regulator of GBM progression, upregulates miR-10b-5p expression, which targets key tumor suppressors like E-cadherin, Apaf-1, and PTEN, thereby enhancing tumor aggressiveness." (PMID 39796267, 2025). "Finally, mutations in APAF1, a gene crucial for the apoptosis pathway, could lead to defects in the apoptotic cascade, disrupting the regulation of cell death, and promoting tumorigenesis and tumor progression." (PMID 40018039, 2025). "Further experiments provided evidence that miR-23a-3p suppresses apoptosis of tumor cells and confers platinum chemoresistance by regulating the expression of its direct target APAF1." (PMID 34283087, 2021). "According to the results of this study, aerobic training has increased the gene expression of cytochrome C, Apaf-1, caspase-3, and caspase-9 in tumor tissue." (PMID 35083006, 2021). "Protein concentrations for PC9, PC3, XIAP and SMAC from n = 120 patient tumours, quantified by reverse phase protein array, together with a median APAF1 expression were used to simulate apoptosis execution." (PMID 32341447, 2020). "The result showed that the expression of APAF1 was related to tumor histological grade by IHC analysis in TMA." (PMID 31131537, 2019).
tumor (continued). "In addition, through functional validation using stable cells expressing variant 1b or 2a fusion forms, we demonstrated that APAF1 inactivation promotes cell survival through inhibition of apoptosis signaling and enhances tumorigenesis, which may trigger an increase in the tumor malignancy of SFT." (PMID 31321477, 2019). "In vitro functional experiments showed that APAF1 depletion increased the tumor potency of cells expressing NAB2-STAT6 fusion protein under treatment with staurosporine." (PMID 31321477, 2019). "A reduction in Apaf-1 occurs during tumor progression from primary to systemic metastasis and can contribute to the ability of tumor cells to evade Caspase-9 apoptotic pathway." (PMID 28399853, 2017). "Apoptotic protease activating factor-1 (Apaf-1), of Caspase-9 apoptotic pathway, is a tumor suppressor gene." (PMID 28479926, 2017). "This is confirmed by the EGb-induced reduction in mRNA expression of TIMP1, Caspase9, Bad, Apaf1, Nrf2, Cat and Nox3 in the Tumor group." (PMID 29197355, 2017). "Conversely, the three X variables with strongest inverse correlation with tumor mass (i.e., lower in larger tumors) were pro-apoptotic proteins Apaf-1, total caspase 3, and Bax." (PMID 27077880, 2016). "Smac, as a novel tumor suppressor, exerts anti-tumor activity via the cytochrome c/Apaf-1/caspase-9 pathway." (PMID 27552933, 2016). "Elevation of APAF1 expression in the tumour tissues from the APAF1-overexpressing group was confirmed using immunohistochemical analysis." (PMID 27021436, 2016). "Apoptosis protease activating factor-1 (Apaf-1) and death-associated protein kinase (DAPK) are apoptosis-related tumor suppressor genes that have generated interest due to their downregulated expression in various tumors." (PMID 23946818, 2013). "In conclusion, the present study is consistent with numerous observations in carcinogenesis that have identified the loss of Apaf-1 and DAPK as a key feature in tumor progression." (PMID 23946818, 2013). "It has been shown that inactivation of Apaf-1 substantially reduces the number of cells required to form tumors in nude mice transplanted with Myc/Ras-transformed fibroblasts, implying that Apaf-1 actually acts as a tumor suppressor." (PMID 22690114, 2012). "This differential sensitivity to cytochrome c is attributed to high Apaf-1 levels in the tumor tissue compared with low levels in the adjacent brain tissue." (PMID 22588980, 2012). "A trend towards a statistically significant correlation was detected by comparing the median NIM levels of APAF-1 and the different tumour stages (P=0.06 and 0.05)." (PMID 17133271, 2006). "In RCC, APAF-1 methylation levels depend on specific characteristics such as tumour size or tumour differentiation." (PMID 17133271, 2006). "The APAF-1 methylation levels in RCC were significantly higher in tumours larger than 4 cm and in high-grade tumours." (PMID 17133271, 2006). "When the NIM levels were compared according to the specific tumour grade of G1/2 or G3, the median NIM levels for APAF-1 in G1/2 (G3) tumours were 34% (51%) in pT1, 55% (58%) in pT2, and 72% (66%) in ⩾pT3 tumours." (PMID 17133271, 2006). "The median NIM levels for APAF-1 were 42% in smaller tumours and 60% in larger ones; the corresponding levels for DAPK-1 were 2 and 3%, respectively." (PMID 17133271, 2006).
tumor (continued). "Tumor Inhibition: The expression of pro-apoptosis genes Bax, Cyt-C, Apaf-1, caspase-9, and caspase-3 was increased when comparing the Western blotting results to the negative control group, while the expression of anti-apoptosis genes Bcl-2 and Livin was decreased." (PMID 40297577, 2025). "Contradictorily, miR-484 could promote apoptosis by targeting Apaf-1, and miR-23b-3p and miR-615-3p could act as either tumor suppressors or oncogenes, which mainly depends on their context." (PMID 36624663, 2023). "LINC00473 is a lncRNA downregulated in CRC that exerts tumor suppressor functions in this disease by promoting apoptotic protease-activating factor 1 (APAF1) IRES activity through competitively sponging miR574-5p and miR15b-5p in tumor initiation and pathogenesis." (PMID 35810318, 2022). "Finally, we also examined APAF1 protein expression by WB in tumor tissue from Skov3 tumor-bearing mice." (PMID 32190895, 2020). "Skov3 cells (all cells treated with paclitaxel) were transfected with miR-27a mimic, APAF1 OE plasmid and co-transfected with miR-27a mimic and APAF1 OE plasmid and implanted subcutaneously into severe combined immunodeficiency mice to allow tumor formation." (PMID 32190895, 2020). "Interestingly, intrinsic apoptotic pathway markers like Apaf1, Bax, and procaspase 9 were upregulated in treated tumor samples compared to untreated control tumor tissue." (PMID 33008036, 2020). "Interestingly, exposure of RCC cell lines (A498 and CCa-5) to 5-aza-2′-deoxycytidine and zebularine effectively inhibited tumor cell growth and re-expressed APAF-1 and DAPK-1 mRNA." (PMID 29706891, 2018). "However, a recent report showing CDC6-mediated inhibition of apoptosome formation through its binding onto cytochrome c-activated Apaf-1, probably explains why senescence emerges as the only tumor suppressor mechanism in our system." (PMID 29321003, 2018). "Moreover, it has been shown to directly interact with RNA-binding protein HuR to enhance the stability of Apaf-1, a major protein in the apotosome, leading to the suppression of tumor cell proliferation." (PMID 26839961, 2016). "We demonstrated previously that although the levels of PC-9 protein were comparable in NSCLC tumours and matched lungs, the expression of both Apaf-1 and PC-3 proteins was frequently upregulated and the induced activity of apoptosome apparatus tended to be higher in the tumours as compared to lungs." (PMID 24626292, 2014). "The APAF-1 methylation level varies according to the tumour stage in TCC of the bladder." (PMID 17133271, 2006). "Thus, APAF-1 methylation levels can help to differentiate between specific tumour stages in TCC and RCC." (PMID 17133271, 2006). "The methylation levels of APAF-1 could differentiate between the individual tumour stages in TCC as well as in RCC." (PMID 17133271, 2006). "Thus, we speculate that binding of this endogenous DNA by Apaf-1, accompanied by impaired Cyt c release in tumor cells, may be an intrinsic driving force for tumorigenesis by triggering NF-κB-driven chronic inflammation." (PMID 39833169, 2025). "However, simultaneous APAF1-OE alleviated the effect of miR-27a on tumor growth." (PMID 32190895, 2020).
tumor (continued). "Notably, numerous TSGs were also reported to be hypermethylated in RCC samples compared to normal tissue (APAF-1, APC, BTG3, CDH1, Gamma-catenin, GATA-3, HOX-B-13, KILLIN, RARβ2, RASSF1A, TIMP3, VHL, and others), associating with increased tumor cell proliferation, invasion, and metastization." (PMID 29706891, 2018). "We previously reported that restoration of TUSC2, a tumor suppressor gene in the 3p21.3 region that has been extensively characterized in 3p21.3-deficient NSCLC cells suppressed tumor growth by induction of apoptosis and alteration of cell kinetics in vitro and in vivo through Apaf-1." (PMID 29296193, 2017). "Therefore, we hypothesized that the BCL11B gene and the PHTF1-FEM1b-Apaf-1 pathway may work together in tumor cell apoptosis." (PMID 26448723, 2015). "The APAF-1 NIM levels could also differentiate between the individual tumour stages (P<0.001)." (PMID 17133271, 2006). "This does not exclude the possibility that, for instance, a loss of Apaf-1 could contribute to tumour development." (PMID 14647151, 2003). "TGF-β1 upregulates miR-10b-5p expression, which downregulates the tumor suppressors E-cadherin, Apaf-1, and PTEN, thereby enhancing tumor aggressiveness in GBM." (PMID 39796267, 2025). "Direct tumor-targeting therapies using proapoptotic proteins (Bax, NOXA, PIG3, APAF1) or tumor suppressors (miR-7, 15-PGDH) are in preclinical or clinical studies." (PMID 36358595, 2022). "miR-21 activates the EGFR/AKT signaling pathway via targeting tumor suppressor genes such as PTEN, PDCD4, APAF1, TPM1, TIMP3, RECK, FOXO1 and SPRY240." (PMID 32019988, 2020). "On the other way, upregulation of miR-21 in NSCLC enhances KRAS-driven tumor initiation via repressing tumor suppressors including programmed cell death 4 (PDCD4) and apoptosis peptidase activating factor 1 (APAF1)." (PMID 32316322, 2020). "The Apaf-1 and DAPK mRNA expression index was decreased in 51 (96.23%) and 50 (94.34%) cases, respectively, in the tumor tissues." (PMID 23946818, 2013). "The Apaf-1 and DAPK gene expression was increased following demethylation, which promoted apoptosis of the tumor cells." (PMID 23946818, 2013). "Further analysis showed that hypermethylation of Apaf-1 (P<0.05) and DAPK (P<0.01) promoter regions correlated with a decreased mRNA expression in the tumor tissues." (PMID 23946818, 2013). "Comparing the median NIM levels of APAF-1 (DAPK-1) revealed a range extending from 41.5% (17.4%) for pT1 to 58% (10.8%) for pT2 and 66% (19.3%) for ⩾pT3 tumours." (PMID 17133271, 2006). "When the tumours were grouped according to their differentiation grade, the median NIM was 20% (53.4%) for APAF-1 in the G1/2 (G3) group and 34.1% (3.6%) for DAPK-1 in the pTa tumours." (PMID 17133271, 2006). "In the G1/2 (G3) group of pT1 tumours, the median NIM was 53.5% (71%) for APAF-1 and 18.3% (24%) for DAPK-1." (PMID 17133271, 2006). "For the muscle-invasive tumour group (⩾pT2, only G3 tumours), the median NIM levels were 97.5% for APAF-1 and 15.8% for DAPK-1." (PMID 17133271, 2006).
tumor (continued). "After the test, it was found that DNMT1 and HDAC1/2 in the tumor tissue were significantly downregulated, while the transcriptional levels of pro-apoptotic genes such as BAX, BNIP3, and APAF1 were significantly increased, and the tumor volume was significantly reduced." (PMID 41335282, 2025). "Besides, HDAC2 knockdown dramatically reduced the capacity of tumor-sphere formation in HDAC2 knockdown GSCs and induced apoptosis by caspase-3, Bax, and Apaf-1." (PMID 35260183, 2022). "Therefore, we considered that PHTF1 has tumor-suppressive activity and triggers the PHTF1-FEM1b-Apaf-1 apoptosis pathway using in vitro assays." (PMID 26448723, 2015). "In favor of this notion, a non-apoptotic role for Apaf-1 was recently proposed, in which it functions as a DNA damage regulator controlling the checkpoint kinase Chk1 and thus acts as a tumor suppressor." (PMID 26290316, 2015). "Two studies have shown that the methylation frequency of APAF-1 gene in the tumor samples is significantly higher compared to their paired normal kidney samples and the expression of APAF-1 is significantly lower in the tumor samples." (PMID 26198328, 2015). "PHTF1 may be a tumor-suppressor like gene and a therapeutic target for triggering the PHTF1-FEM1b-Apaf-1 apoptosis pathway." (PMID 26448723, 2015). "Hypermethylation of DcR1 (28.4%), but not death receptors (DR4 and DR5) and other TRAIL signalling-related genes (APAF1, CASP8 and DcR2) in our study indicates the potential use of recombinant TRAIL or TRAIL receptor agonistic monoclonal antibodies as selective anti-tumour therapy in CCA." (PMID 21448164, 2011). "Comparing RCC specimens according to their differentiation grade revealed a correlation between higher (G1/2) and lower (G3) differentiation; APAF-1 methylation levels compared as median NIM levels were 41% for high-grade and 55% for low-grade tumours (P=0.05)." (PMID 17133271, 2006). "In the patient group with RCC, the methylation frequency was 100% for APAF-1 irrespective of the tumour stage." (PMID 17133271, 2006). "This was also the case in RCC, where tumour characteristics like size and differentiation, but not the nodal status, differed according to the specific APAF-1 NIM levels." (PMID 17133271, 2006). "The median methylation levels for APAF-1 were 51% in node-negative tumours and 58% in node-positive tumours, the corresponding NIM levels for DAPK-1 being 2 and 9%, respectively." (PMID 17133271, 2006). "Tumours with negative or weak Apaf-1 expression were distributed fairly evenly among the various Breslow thickness categories (P>0.05, χ2 test)." (PMID 15305193, 2004). "Besides, miR-21-5p enhances the cellular growth and drug resistance of tumor cells by targeting PTEN (phosphatase and tensin homolog), P21 (account for cell cycle arrest), PCD (programmed cell death), and apoptotic protease activating factor 1 (APAF1)." (PMID 35550636, 2022). "Therefore, studies with regard to the expression of Apaf-1 and DAPK in OSCC may contribute to exploring the anti-apoptotic pathway of tumor cells and may also provide guidance for future treatment." (PMID 23946818, 2013).